CADM4 (cell adhesion molecule 4)
Description:
Cell adhesion molecule, exhibiting calcium- and magnesium-independent cell-cell adhesion activity. In its palmitoylated form, is required for proper oligodendrocyte maturation and myelination in CNS via its association with other cell adhesion molecules such as CADM2/3 and MAG (By similarity). May have tumor-suppressor activity.
Synonyms: IgSF4C; NECL-4; NECL4; TSLL2; SynCAM4
Tractability: Antibody: UniProt predicts a signal peptide or a membrane-spanning region; the Human Protein Atlas places it where antibodies can reach. PROTAC: ubiquitination databases record sites on it; its protein half-life has been measured.
Gene: Protein-coding gene on chromosome 19 (43,622,366 to 43,639,850, reverse strand). Ensembl gene ENSG00000105767.
Subcellular location: Cell membrane; Golgi apparatus membrane
Subcellular location (Human Protein Atlas): Plasma membrane; Cytosol; Nucleoplasm
Gene Ontology:
Molecular function: protein binding; vascular endothelial growth factor receptor 2 binding; protein phosphatase binding; receptor tyrosine kinase binding; vascular endothelial growth factor receptor 1 binding
Biological process: negative regulation of peptidyl-threonine phosphorylation; negative regulation of peptidyl-tyrosine phosphorylation; negative regulation of protein phosphorylation; regulation of cell motility; regulation of cell population proliferation; regulation of protein phosphorylation; regulation of Rac protein signal transduction; regulation of wound healing; central nervous system myelination; homophilic cell-cell adhesion; negative regulation of vascular endothelial growth factor receptor signaling pathway; negative regulation of vascular endothelial growth factor signaling pathway; oligodendrocyte differentiation
Cellular component: cell leading edge; cell-cell contact zone; Golgi membrane; plasma membrane
Genetic constraint (gnomAD): Loss-of-function variants: 13 observed, 41.7 expected, observed/expected ratio (o/e) 0.31, 90% interval 0.2 to 0.5. The upper end of that interval is the gene's LOEUF score, 0.5, which puts it in group 2 of 6, group 1 being the genes least tolerant of losing a copy. Missense variants: 419 observed, 529.22 expected, observed/expected ratio (o/e) 0.79, 90% interval 0.73 to 0.86. Synonymous variants: 209 observed, 222.82 expected, observed/expected ratio (o/e) 0.94, 90% interval 0.84 to 1.05.
Homologues: Orthologues: chimpanzee CADM4 (100% identical), macaque CADM4 (100% identical), dog CADM4 (99% identical), mouse Cadm4 (98% identical), pig CADM4 (95% identical), rabbit CADM4 (94% identical), guinea pig CADM4 (94% identical), rat Cadm4 (94% identical), tropical clawed frog cadm4 (70% identical), zebrafish cadm4 (59% identical), Drosophila melanogaster Fas3 (20% identical). Paralogues in human: CADM1 (41% identical), CADM2 (38% identical), CADM3 (35% identical), NECTIN1 (22% identical), NECTIN4 (22% identical), PVR (21% identical), NECTIN2 (20% identical), NECTIN3 (20% identical), CRTAM (15% identical), CD226 (14% identical), CD200 (10% identical), TIGIT (9% identical), and 2 more.
Diseases named in the same sentence as CADM4 in open-access papers:
CADM4 is named in the same sentence as 30 diseases in open-access papers, as found by Europe PMC text mining. Sharing a sentence is not in itself a finding about the gene and the disease. The quoted sentences say what the papers report.
non-small cell lung carcinoma (3 papers, 2022 to 2024). A group of at least three distinct histological types of lung cancer, including non-small cell squamous cell carcinoma, adenocarcinoma, and large cell carcinoma. "Loss of or reduced CADM4 expression has been found in cancer cells, including glioma, prostate cancer, renal cell carcinoma, and non-small cell lung cancer; thus, CADM4 has been recognized as a candidate tumor suppressor." (PMID 37108061, 2023). "A study on cell adhesion molecule 4 (CADM4) showed that CADM4 can impede the proliferation and spread of non-small cell lung cancer (NSCLC) cells by blocking the Akt signaling pathway." (PMID 39668834, 2024).
gallbladder cancer (2 papers, 2023 to 2024). "The expression of CADM4 in gallbladder cancer has been observed to have a negative correlation with the poor prognosis of individuals with this type of cancer." (PMID 39668834, 2024). "The role of CADM4 in gallbladder cancer (GBC) has not been reported." (PMID 37108061, 2023).
gastric cancer (2 papers, 2022 to 2023). A primary or metastatic malignant neoplasm involving the stomach. "Therefore, in this study, we investigated the associations between CADM4 expression and clinicopathological features of gastric cancer by performing immunohistochemical (IHC) staining on a large series of resected samples." (PMID 35453989, 2022). "Two previous studies have reported the expression of CADM4 in gastric cancer." (PMID 35453989, 2022). "In a previous study of gastric cancer, low CADM4 expression was more frequently observed in tumors without HER2 amplification." (PMID 37108061, 2023). "The prognostic implications of CADM4 in gastric cancer have not been conclusively elucidated." (PMID 35453989, 2022).
lymph node metastasis (2 papers, 2022 to 2023). "In univariate analyses, low CADM4 expression (p = 0.002), advanced T category (p = 0.001), lymph node metastasis (p = 0.002), high AJCC stage (p < 0.001), lymphovascular invasion (p = 0.004), and perineural invasion (p = 0.004) were predictors of short OS." (PMID 37108061, 2023). "In addition, low CADM4 expression (p = 0.023), advanced T category (p < 0.001), lymph node metastasis (p = 0.001), high AJCC stage (p < 0.001), lymphovascular invasion (p < 0.001), and perineural invasion (p = 0.001) were predictors of short RFS." (PMID 37108061, 2023).
adult T-cell leukemia (1 paper, 2018). "Next, we examined the interaction between CADM1 and CADM4 in cell spreading assay using a cell line, ATN1, which is derived from adult T-cell leukemia (ATL) expressing a high amount of CADM1 protein." (PMID 30131958, 2018).
Anxiety (1 paper, 2024). Intense feelings of nervousness, tension, or panic often arise in response to interpersonal stresses. "The results demonstrated that both Cadm4-KI and ZDHHC3-KO mice exhibited impairments in learning and memory, as well as altered behavior in anxiety-like tasks when compared to WT mice." (PMID 39327467, 2024).
demyelination (1 paper, 2024). "Unexpectedly, alterations in Cadm4 palmitoylation are closely linked to neuroinflammation in various demyelination mouse models." (PMID 39327467, 2024).
demyelination diseases (1 paper, 2024). "The downregulation of Cadm4 (Cell adhesion molecular 4) is a prominent feature in demyelination diseases, yet, the underlying molecular mechanism remains elusive." (PMID 39327467, 2024). "Despite these associations, the precise molecular mechanisms governing Cadm4 regulation and its role in demyelinating diseases remain inadequately understood." (PMID 39327467, 2024). "Interestingly, our data showed that the levels of palm-Cadm4 and ZDHHC3 are downregulated in both LPS and EAE models, suggesting that ZDHHC3-Cadm4 signaling may represent a conserved pathological mechanism underlying various demyelination diseases." (PMID 39327467, 2024).
gastric adenocarcinoma (1 paper, 2022). "In conclusion, we demonstrate the associations between low CADM4 expression and aggressive clinicopathological features and clinical outcomes for gastric adenocarcinoma." (PMID 35453989, 2022). "In our study, we evaluate CADM4 expression in a large series of patients with gastric adenocarcinoma." (PMID 35453989, 2022). "CADM4 can act as a tumor suppressor in gastric adenocarcinoma and can be considered a prognostic biomarker." (PMID 35453989, 2022). "CADM4 can act as a tumor suppressor in gastric adenocarcinoma." (PMID 35453989, 2022). "Therefore, we evaluated the clinicopathological significance and prognostic value of CADM4 expression in a large series of patients with gastric adenocarcinoma." (PMID 35453989, 2022). "In this study, we performed IHC staining with CADM4 antibody on 534 gastric adenocarcinomas." (PMID 35453989, 2022). "Immunohistochemical staining for CADM4 was performed on 534 gastric adenocarcinomas." (PMID 35453989, 2022). "CADM4 expression was reduced or absent in 303 of 534 gastric adenocarcinomas." (PMID 35453989, 2022).
liver cancer (1 paper, 2017). An epithelial or non-epithelial malignant neoplasm that arises from the liver. "We also demonstrated that two additional genes without a prior known role in liver cancer, CADM4 and THRSP, have strong anti-tumorigenic activity in this tumor type." (PMID 28273073, 2017).
T-cell leukemia (1 paper, 2018). A malignant disease of the T-lymphocytes in the bone marrow, thymus, and/or blood. "SPRi analysis identified a new interaction between CADM1 and CADM4, where this heterophilic interaction was shown to be involved in morphological spreading of adult T-cell leukemia (ATL) cells expressing CADM1 when incubated on CADM4-coated glass." (PMID 30131958, 2018).
tumor (15 papers, 2012 to 2023). "Low CADM4 expression was associated with tumor invasiveness and poor clinical outcomes in patients with GBC." (PMID 37108061, 2023). "Similar to these results, a decrease in or loss of expression of CADM4 in tumor cells was associated with aggressive clinicopathological phenotypes and poor prognosis, suggesting the potential of CADM4 as a tumor suppressor." (PMID 35453989, 2022). "Complementary to the loss-of-function experiments, SHP, DKK4, or CADM4 overexpression significantly reduced tumor formation in immunocompromised mice." (PMID 28273073, 2017). "Moreover, the CADM4 expression was decreased in carcinomas with vascular infiltration, suggesting that loss of the CADM4 is involved in tumour angiogenesis and invasion." (PMID 22453032, 2012). "Cell adhesion molecule 4 (CADM4) is involved in intercellular interactions and is a tumor-suppressor candidate." (PMID 37108061, 2023). "The authors also identified that the downregulation of CADM4 in tumor cells promotes hemidesmosome disassembly, leading to tumor cell invasion and metastasis." (PMID 37108061, 2023). "Cell Adhesion Molecule 1 (CADM1), CADM2, CADM3 and CADM4, serve as tumor suppressors and can inhibit cancer cell proliferation and induce apoptosis." (PMID 31480483, 2019). "CADM1 is ectopically expressed in ATL and promotes tumor growth and infiltration, whereas CADM4 is expressed in endothelial cells." (PMID 30131958, 2018). "This study is the first in which CADM4 expression in human GBC tissues was evaluated and, similar to other human cancer studies, the results indicated that CADM4 may play a crucial role in GBC as a tumor suppressor and prognostic biomarker." (PMID 37108061, 2023). "The role of CADM4 in tumor growth and invasion has been studied in several types of tumors." (PMID 37108061, 2023). "Cell adhesion molecule 4 (CADM4) is a novel tumor suppressor candidate." (PMID 35453989, 2022). "CADM4 is a potential prognostic biomarker and is thought to play a role as a tumor suppressor." (PMID 35453989, 2022). "Moreover, overexpression of CADM4 was sufficient to reverse tumor acceleration by SRC-2 knockdown in HepG2 cells." (PMID 28273073, 2017). "Interestingly, comprehensive data from Wang’s and our own datasets indicate that SHMT2 might enhance ccRCC tumorigenesis while impairing tumor thrombus invasion, whereas CADM4 possibly exerts opposite effects on tumorigenesis and thrombus invasion." (PMID 37328520, 2023). "Animal studies showed that the mean size of tumors with CADM4 or protein DAL-1/4.1B deficiency was significantly larger than those expressing both CADM4 and 4.1B, explaining that their cascade response may affect intercellular adhesion, i.e., CADM4-4.1B can influence tumor invasion." (PMID 36835189, 2023). "First, two tumor suppressors caught our attention: the thioredoxin-interacting protein TXNIP and the cell adhesion molecule CADM4." (PMID 37367050, 2023). "CADM4 shows significant homology with TSLC1, including a short cytoplasmic domain that is considered to play a critical role in tumor suppressor activity." (PMID 35453989, 2022). "Several studies showed that NB metastatic cells express distinctive features from primary tumor cells, including down-regulation of several tumor suppressor genes (i.e., SIRT6, BBC3/PUMA, STK11, CADM4 and GLTSCR2) and up-regulation of immunosuppressive molecules, such as calprotectin and HLA-G." (PMID 33921337, 2021). "Thus, multiple SRC-2 target genes, including SHP, CADM4, and DKK4, exhibit tumor suppressor activity in human HCC cells." (PMID 28273073, 2017). "Indeed, enforced expression of SHP, CADM4, DKK4, and THSRP in combination significantly reduced proliferation and tumor burden." (PMID 28273073, 2017). "We show here that nectin-like molecule-4/cell adhesion molecule 4, known to serve as a tumour suppressor, interacts with ErbB3 in the absence of HRG and inhibits the HRG-induced dimerization of ErbB3 with ErbB2 and its activation." (PMID 28900130, 2017).
tumor (continued). "Based on their different expression patterns among normal-tumor-thrombus triples, RAB25 and GGT5 were supposed to play a consistent role in both tumorigenesis and invasion processes, while SHMT2 and CADM4 might play the opposite roles in tumorigenesis and thrombus invasion." (PMID 37328520, 2023).
cancer (12 papers, 2010 to 2025). A tumor composed of atypical neoplastic, often pleomorphic cells that invade other tissues. "CADM4 was described as a tumor suppressor gene in multiple cancers, including PCa, while Roundabout homolog 4 (ROBO4) is a transmembrane receptor specifically expressed in endothelial cells." (PMID 40136513, 2025). "In the case of TXNIP, decreased levels prevent the clearance of oxidative species within the cells, while reduced levels of CADM4 limit the interaction with the extracellular matrix in cancer cells." (PMID 37367050, 2023). "CADM4 expression is also irreversibly down-regulated in cancer cells in several studies, and there is a possibility of a decrease in CADM4 expression due to DNA methylation, but further study is needed." (PMID 35453989, 2022). "In vitro studies on several types of cancer, including prostate cancer, glioma, colon cancer, renal cell carcinoma, and lung cancer, showed that CADM4 was overall down-regulated." (PMID 35453989, 2022). "CADM3 and CADM4 were upregulated in most cancers, whereas NECTIN2 was downregulated in most cancers." (PMID 34925438, 2021). "CADM4 may play an important role in cancer progression and patient survival and can be used as a potential prognostic marker of GBC." (PMID 37108061, 2023). "Therefore, there have been several studies on CADM4 expression in cancer cells and its role in the development or progression of cancer." (PMID 35453989, 2022). "In addition, overexpression of CADM4 was efficient in suppressing the tumorigenicity of cancer cells." (PMID 35453989, 2022).
adenocarcinoma (1 paper, 2022). A common cancer characterized by the presence of malignant glandular cells. "We evaluated the associations between CADM4 expression and the clinicopathological and molecular characteristics of the adenocarcinomas." (PMID 35453989, 2022).
neurological disorders (1 paper, 2024). "By advancing our understanding of the molecular mechanisms governing Cadm4 regulation and its role in myelination, our research aims to provide new insights and approaches for addressing these challenging neurological disorders." (PMID 39327467, 2024).
CADM4 also shares sentences with these, for which no sentence is quoted: breast cancer (3 papers); renal cell carcinoma (3); colon cancer (2); neuroblastoma (2); prostate carcinoma (2); small intestinal adenocarcinoma (2); atherosclerosis (1); colorectal adenocarcinoma (1); experimental autoimmune encephalomyelitis (1); glioma (1); hepatocellular carcinoma (1); kidney cancer (1); lung carcinoma (1); pancreatic ductal adenocarcinoma (1); prostate tumor (1).